HMGB1 (high mobility group box 1)
Diseases named in the same sentence as HMGB1 in open-access papers (continued):
Sharing a sentence is not in itself a finding about the gene and the disease.
tumor (continued). "Indeed, we recently uncovered a specific interaction between dying and remnant live cells through a specific HMGB1/TLR4-RAGE pathway that induces sCLU in the live cells to develop chemoresistance in tumor cells." (PMID 27405665, 2016). "In addition, it was previously demonstrated that miR-142-3p functioned as a potential tumor suppressor directly targeting HMGB1 in non-small-cell lung carcinoma cells." (PMID 27563308, 2016). "To investigate whether SK-induced ICD is via the suppression of hnRNPA1 activity, we compared the change in expression patterns of specific ICD markers, including HSP70 and HMGB1, in response to SK treatment in tumor cells." (PMID 27248319, 2016). "Within this core, dying/necrotic or surviving/hypoxic GemOE tumor cells release Ac-HMGB1." (PMID 26989079, 2016). "Secreted Ac-HMGB1 in autocrine/paracrine fashion promotes survival of GemOE/TNBC tumor cells." (PMID 26989079, 2016). "The presence of HMGB1 in the context of the NK:tumor cell interaction may also play a role in the progression of the tumor." (PMID 27294158, 2016). "We speculated that HMGB1 released in the TME might potentiate the effects of hypoxia in less hypoxic areas of the tumor." (PMID 26925422, 2016). "We measured the expression of HMGB1 and CD68 in tumoral and peritumoral liver tissues after curative resection and assessed the impacts of the tumor-associated macrophage (TAM) count and HMGB1 expression on clinicopathologic characteristics, overall survival (OS), and recurrence-free survival (RFS)." (PMID 27836008, 2016). "Activation of TLR2 with LTA and LTA + HMGB1 resulted in significantly increased tumor cell proliferation in MIAPaCa-2 cells (120% and 123%, p < 0.05), BxPC-3 cells (117% and 132%, p < 0.0001) and PaCaDD135 cells (117% and 114%, n.s. and p < 0.005) compared to untreated cells." (PMID 27941651, 2016). "Thus, HMGB1 from both tumor and immune cells can accumulate in the tumor microenvironment and sustain inflammation, cytokine release, cell proliferation, and recruitment of immune cells." (PMID 27294158, 2016). "CRT and HMGB1 were stained in the nucleus of most tumor cells." (PMID 27363018, 2016). "After PDT treatment, both CRT and HMGB1 were significantly stained in the tumor cells." (PMID 27363018, 2016). "Finally, HMGB1 promotes tumor infiltration by lymphotoxin α1β2-producing T cells which recruit M2-type macrophages that support tumor angiogenesis and growth." (PMID 26925422, 2016). "Together show that whether diffused out of necrotic GemOE cells or released from hypoxic GemOE cells within tumor cores, Ac-HMGB1 upregulates CXCR4 on the surface of MSCs most likely through activation of RAGE." (PMID 26989079, 2016). "Moreover, compelling evidences have further confirmed that HMGB1 over-expression is closely related to tumor development by mediating the proliferation, invasion and migration of cancer cells." (PMID 27116470, 2016). "However, HMGB1 acts as both a tumor suppressor and an oncogenic factor in tumorigenesis and cancer therapy depending on the context and HMGB1 location and modification." (PMID 27391431, 2016). "The constant release of HMGB1 from necrotic tumor cells may create a microenvironment resembling chronic inflammation; a condition known to contribute to the development of epithelial malignancies, especially inflammation-associated cancer." (PMID 27116470, 2016). "High-mobility group protein B1 (HMGB1) is a chromosomal protein promoting tumor progression." (PMID 27323831, 2016). "Moreover, inducing immunogenic tumor cell death by ethanol treatment ectopically induces calreticulin and high-mobility group box 1 (HMGB1), which activate DCs." (PMID 27240347, 2016). "For example, the reduced form of HMGB1 released from dying cells could trigger dendritic cells to induce anti-tumor immune response, while the oxidized form of HMGB1 would be unable to activate the immune response." (PMID 27206676, 2016).
tumor (continued). "In addition to its cytotoxic effects, it also contributes to the antitumor immune response by promoting the release of tumor cell antigens such as heat shock proteins and high mobility group box 1 after tumor cell necrosis." (PMID 27835886, 2016). "LPS and Hmgb1 activated NF-κB and enhanced tumor cell proliferation." (PMID 27779100, 2016). "In addition, also NK cells can actively release HMGB1 in the context of the NK:DC cross talk or upon the engagement of different activating NK cell receptors, including those mainly involved in tumor cell recognition." (PMID 27294158, 2016). "HMGB1 could enhance tumor-cell invasion and promote angiogenesis by supporting the protumoral functions of TAMs by a RAGE-dependent mechanism." (PMID 27836008, 2016). "Analysis of dissociated tumours by flow-cytometry revealed a significant increase in the total number of TAMs and a slight but significant decrease in the total number of neutrophils in HMGB1-shRNA-transduced B16 tumours." (PMID 27426915, 2016). "Most of that evidence is based on the direct effects of HMGB1 on tumor cells." (PMID 27836008, 2016). "In addition, HMGB1 serves a pivotal role in the maturation of DCs and favors both processing and the presentation of tumor antigens to naïve T cells, thereby establishing a link between innate and adaptive anti-tumor immune responses." (PMID 26881822, 2016). "Thus, we assessed the translocation of Calreticulin (CRT) from the lumen of ER vesicles to the surface of tumor cells and the release of HMGB1, key hallmarks of ICD." (PMID 27028869, 2016). "Moreover, pharmaceutical inhibition of glutaminolysis sensitizes tumour cells to HMGB1 providing a basis for a therapeutic strategy for treating cancer." (PMID 26948869, 2016). "Furthermore, our study showed that HMGB1 in the supernatant of tumor cells treated with PV-10 was responsible for the up-regulation of CD40 expression on BM-derived DCs and for the increased ability of DC to stimulate T cell activation." (PMID 27177220, 2016). "It is now clear that HMGB1 induced autophagy promotes tumor resistance to chemotherapy." (PMID 26925422, 2016). "In addition to mediating the altered inflammatory and metabolic response, several nuclear DAMPs, including HMGB1 and histones (current study), can also promote tumor cell migration, invasion, and metastasis." (PMID 27623211, 2016). "Therefore, extracellular HMGB1 sustains an inflammatory microenvironment within tumors that supports tumor growth, invasion, and metastasis." (PMID 27493669, 2016). "Similarly, western blotting (WB) analyses showed that the expression of HMGB1 protein was higher in BUC tissues compared with paired adjacent non-tumour tissues (0.262 ± 0.109 vs. 0.129 ± 0.111, P < 0.05, Fig. 1B1, B2)." (PMID 26239046, 2015). "Necrotic cells may attract macrophages into the tumor, and activated macrophages could release high mobility group box 1 (HMGB1) outside the necrotic cells." (PMID 26512660, 2015). "On the other hand, HMGB1 extracellularly has been demonstrated to have a role in inflammatory processes, neural outgrowth, smooth muscle cell chemotaxis, migration and proliferation of mesoangioblast cells, and cell proliferation in tumor and metastasis." (PMID 26798204, 2015). "Moreover, extracellular reducible HMGB1 has been shown to induce autophagy and promote tumor resistance to alkylators, tubulin disrupting agents, DNA cross-linkers, and DNA intercalators in human pancreatic cancer and colon cancer cell lines." (PMID 25622595, 2015). "However, it is still unclear how tumors manage to effectively utilize the tumor promoting functions of the ATP/HMGB1/caspase-1 system while successfully evading immune-mediated destruction." (PMID 26552848, 2015). "The next step was to identify the receptor(s) expressed on DU145 tumor cells that could account for HMGB1 triggering of sCLU production." (PMID 26469759, 2015).
tumor (continued). "Furthermore, HMGB1 release from tumor cells can suppress naturally acquired CD8 T-cell antitumor response by promoting regulatory T-cells to produce immunosuppressive IL-10." (PMID 26854151, 2015). "This increased release of HMGB1 correlated with the percentage of necrotic tumor cells." (PMID 25973681, 2015). "MyD88 KO mice have defects in TLR signaling and our results show that zVAD-fmk did not further retard growth of B16 tumors treated with RT, DTIC and HT in these mice, again indicating that HMGB1 in vivo is a key player in zVAD-fmk-induced anti-tumor immune responses." (PMID 25973681, 2015). "The HMGB1 released from dying cells could be a new marker to predict the possibility of tumor repopulation." (PMID 25986235, 2015). "However, the effect of the drug was partially abrogated when tumor cells were preincubated with HMGB1 (100 ng/mL)." (PMID 25385222, 2015). "To determine whether HMGB1 could induce tumour angiogenesis, we incubated HUVECs with CM from HCT116 cells in a tumour-like microenvironment." (PMID 26099505, 2015). "Thus, it seems reasonable that HMGB1 has become an attractive target for the suppression of tumour angiogenesis." (PMID 26099505, 2015). "Exposure to HMGB1 was found to induce significant levels of sCLU in DU145 tumor cells." (PMID 26469759, 2015). "It has been suggested that the overexpression of HMGB1 may promote certain genes to form a tumor phenotype, rendering the cells immune to apoptosis and resulting in tumorigenesis." (PMID 25574225, 2015). "DCs loaded with purified autophagosomes from autophagic tumor cells induced tumor-specific immune responses, and autophagy regulated selective release of high-mobility group B1 (HMGB1), which acted as an endogenous pattern recognition receptor (PRR) to induce DC maturation." (PMID 26167495, 2015). "However, there are conflicting roles of HMGB1 acting as both a tumor suppressor and an oncogenic factor in cancer." (PMID 26393575, 2015). "With its manifold functions in tumor development as well as in immune response, HMGB1 represents the two-faced role of the immune system in general: while an inflammatory microenvironment promotes tumor growth, effective immune recognition results in the effective elimination of malignant cells." (PMID 26854151, 2015). "The superior dose distribution and strong DNA-damaging effects of carbon-ion beams mean that it may be possible to induce HMGB1 release only within the tumor microenvironment." (PMID 25755254, 2015). "The live tumor cells in contact with the dying cell still retained HMGB1 in the nucleus." (PMID 26469759, 2015). "Evidence suggests that endogenous HMGB1 is a critical regulator of autophagy in tumor cells." (PMID 25652880, 2015). "HMGB1 then potentiates angiogenesis, tumor initiation, promotion and progression." (PMID 26512660, 2015). "We tested whether HMGB1 inhibition alone was sufficient to account for the antichemoattractant activity and reduced tumor growth or whether other aspirin activities were also required." (PMID 26068794, 2015). "In addition to its role in the nucleus, extracellular HMGB1 has key roles in inflammation, cell differentiation, cell migration, and tumor metastasis." (PMID 26486085, 2015). "To prove that HMGB1 released from dying cells could bind a neighboring tumor cell to trigger sCLU and result in protection against DTX, we used immunohistochemistry to depict the molecules involved on a cell-by-cell basis." (PMID 26469759, 2015). "In this study, we investigated whether high mobility group box 1(HMGB1) is also involved in tumor repopulation." (PMID 25986235, 2015). "Indeed, it has been shown that HMGB1 released by dying tumor cells activates DC via TLR4 enhancing the efficacy of anti-tumor CTL responses." (PMID 26075613, 2015). "When this supernatant was added to freshly-plated DU145 tumor cells, it effectively raised cytoplasmic sCLU levels which could be markedly reduced by the presence of anti-HMGB1." (PMID 26469759, 2015).
tumor (continued). "However, HMGB1 expression significantly correlated with the histological type of the tumor (P = 0.02), lymphatic invasion (P = 0.02), and venous invasion (P = 0.05)." (PMID 25622595, 2015). "We have recently demonstrated that inflammatory infiltrates present in papillary cancer are high in HMGB1 that may contribute to tumor transformation and escape immune surveillance." (PMID 26106610, 2015). "In order to test our concept that HMGB1 from necrotic tumor cells can induce sCLU from live tumor cells, we next collected supernatants from DU145 tumor cells pretreated with DTX for 6 h and then washed free of DTX before reincubation for 24 h in drug-free medium." (PMID 26469759, 2015). "HMGB1 is released from tumor cells undergoing classical necrotic cell death." (PMID 25652880, 2015). "HMGB1 has been found in most of human tumors and it is closely related with tumor development." (PMID 25574225, 2015). "In addition to the “eat me” signals on dying tumor cells, co-stimulatory DAMPs are required to generate an effective anti-tumor immune response (most commonly ATP and HMGB1)." (PMID 26486085, 2015). "Interestingly, tumor-derived exosomes obtained from stressed tumor cells are shown to be highly immunogenic, possibly due to the enrichment of danger signals such as uric acid and HMGB1 in the vesicles under stress condition." (PMID 26343191, 2015). "Thus, overexpression of HMGB1 and its receptor RAGE is observed in several cancers and is associated with tumor growth and metastasis." (PMID 26500646, 2015). "To further evaluate the possible specific roles of the DAMP components in the ICD-associated activities of shikonin-treated tumor cells, we next compared the changes in expression of major ICD components, HSP70, CRT and HMGB1, in 4 T1 cells in response to SK treatment." (PMID 26403780, 2015). "Furthermore, there was a positive correlation between HMGB1 serum levels and tumor size and TNM stage." (PMID 26854151, 2015). "Recent discoveries suggest that autophagy regulates selective HMGB1 release in tumor cells." (PMID 25652880, 2015). "Since HMGB1 is reported to have paradoxical effects on tumor progression by affecting both the cancer cells and the tumor immunity, the counter-balance between these two effects may be important in determining the final effect." (PMID 25622595, 2015). "HMGB1 could not be identified as an effective predictive factor for CRT, because only tumor tissues obtained after CRT were used for immunohistochemical staining of HMGB1, and immunostaining of HMGB1 may be affected by CRT itself." (PMID 25622595, 2015). "However, HMGB1-pretreated DU145 tumor cells showed less colocalization of activated Bax to mitochondria, when treated with DTX (last row)." (PMID 26469759, 2015). "Immunogenic forms of tumor cell death induced by X-rays might include immune modulating danger signals like heat shock protein 70, adenosine triphosphate, and high-mobility group box 1 protein." (PMID 26346226, 2015). "And also HMGB1 may support tumor growth and metastasis though its ability as an extracellular ligand and/or its pro-inflammatory properties as a damage-associated molecular pattern to induce proliferation or angiogenesis." (PMID 25051367, 2014). "Therefore, HER2 positive CSCs promote their own self-renewal, by upregulating TLR2 and secreting its endogenous ligand HMGB1, and generate a favorable microenvironment for tumor progression." (PMID 25136593, 2014). "Hypoxia may up-regulate the expression of high-mobility group box protein-1 (HMGB-1), that acts as extracellular signaling molecule during inflammation, angiogenesis, cell differentiation, cell migration, and tumor metastasis." (PMID 25362644, 2014). "Lastly, HMGB1 inhibits antitumor immunity for tumor survival." (PMID 25356587, 2014).
tumor (continued). "First involves blocking HMGB1 activity which is conducive towards tumor growth." (PMID 24487722, 2014). "In addition to its role in the nucleus, HMGB1 also functions in the cytoplasm as an extracellular signaling protein during inflammation, cell differentiation and tumor progression." (PMID 24996221, 2014). "Radiation induced secretion of ATP and HMGB1 in both dying and surviving tumor cells." (PMID 24480782, 2014). "In the process of tumor progression, HMGB1 has been shown to inhibit dendritic cells in the tumor microenvironment, indicating that HMGB1 may participate in tumor evasion and in the promotion of cancer development." (PMID 24837834, 2014). "Indeed, most tumor cells from hCD31 mAb treated mice expressed HMGB-1, that was barely detectable in control tumors, suggesting that hypoxia augmented by hCD31 mAb treatment up-regulated HMGB-1." (PMID 25362644, 2014). "It is tempting to speculate that HMGB-1 synergizes with hypoxia sub-serving the same or similar functions in less hypoxic or normoxic areas of the tumor mass." (PMID 25362644, 2014). "Interestingly, HMGB1 can also be released by MM tumor cells that become “addicted” to HMGB1 for the maintenance of the transformed phenotype (i.e., tumor cell invasiveness and motility, anchorage-independent growth, etc.)." (PMID 28548074, 2014). "This is a very important observation since HMGB1 is not only secreted by CSCs but also secreted by activated dendritic cells (DCs) and necrotic cells and thus is one of the most important molecules driving tumor escape from cytotoxic treatment." (PMID 25136593, 2014). "TLR2 plays an important role in the induction of tumor regression, which has been demonstrated in a mouse model of glioblastoma multiforme where blocking HMGB1-mediated TLR2 signaling via tumor-infiltrating myeloid DCs resulted in a loss of therapeutic efficacy." (PMID 24744758, 2014). "An intriguing novel observation has reported by Kono and colleagues who demonstrated that 38% of patients with oesophageal squamous cell carcinoma harbored elevated HMGB1 serum levels after chemoradiotherapy and showed concomitant tumor antigen-specific T cell responses." (PMID 23378947, 2013). "Irradiation of tumors has been shown to impair on the one hand the immunosuppressive action of the tumor and on the other to induce so-called “immunogenic” cell death within the tumor with translocation of calreticulin to the plasma membrane, release of HMGB1 or ATP." (PMID 23966948, 2013). "Furthermore, recombined mouse IL-23 administration abrogated the reduced IL-17 expression and decreased tumor size induced by Hmgb1 inhibitor." (PMID 24453427, 2013). "The same study revealed an upregulated HMGB1 expression within the tumor microenvironment in patients with ESCC after preoperative chemoradiotherapy, but not in those without chemoradiotherapy, and the degree of HMGB1 positively correlated with patient survival." (PMID 23378947, 2013). "Because HMGB1 and VEGF-C expression were both significantly associated with tumor invasion and metastasis in GC, we further investigated whether these two immunohistochemical markers could be used as prognostic predictors for GC." (PMID 23866030, 2013). "The source of extracellular HMGB1 needs to be further characterized, whether arising from stressed tumor cells or recruited inflammatory cells, including NK cells or DCs, or all." (PMID 23519706, 2013). "HMGB1 is essential for infiltration and activation of T-cells expressing lymphotoxin α1β2(LT) in mice with prostate cancer, therefore recruiting macrophages to promote tumor malignant progression." (PMID 23519706, 2013). "Overexpression of HMGB1 has been observed in several human tumor types." (PMID 23426143, 2013). "Furthermore, HMGB1 is able to induce maturation of DCs, implying that chemoradiation induces tumor antigen-specific T cell responses, and that chemoradiation-mediated HMGB1 production is related to clinical outcome." (PMID 23378947, 2013).